GPX4 (glutathione peroxidase 4)
Diseases named in the same sentence as GPX4 in open-access papers (continued):
Sharing a sentence is not in itself a finding about the gene and the disease.
cancer (continued). "Cells, especially cancer cells with high metabolic rates, appear to continually suffer the threat of lipid ROS, and inhibiting GPX4 causes rapid accumulation of lipid ROS and oxidative damage." (PMID 38070189, 2024). "Iron dependency is a characteristic of cancer cells; excessive ionic iron causes “iron enrichment” and leads to ferroptosis, which is a new cell death mode characterized by GPX4 inactivation and ROS accumulation." (PMID 36732567, 2023). "Differently to Dt, in cancer cells treated with erastin and GPX4-deficient mouse cells, the accumulation of L-ROS, consumption of PUFAs and subsequent cell death can be prevented by treatment with small molecular antioxidants." (PMID 36829917, 2023). "The downregulation of system Xc− and GPX4 has been implicated in the ferroptotic response of cancer cells." (PMID 37056514, 2023). "It should be noted that the first three classes of ferroptosis inducers are strongly associated with GPX4, which indicates the vast potential of GPX4 inhibiting cancers via ferroptosis." (PMID 36675129, 2023). "Different studies have shown that proferroptotic compounds target key elements of iron metabolism, such as the Xc− and GPx4 systems, causing iron dyshomeostasis and triggering ferroptosis, leading cancer cells to their death." (PMID 38139106, 2023). "This led us to explore the potential mechanisms underlying GPX4 involvement in cancer immunotherapy." (PMID 38065948, 2023). "Several therapeutic oncology regimens are highly susceptible to GPX4 inhibition, highlighting the importance of GPX4 inhibitors in targeting ferroptosis in cancer." (PMID 36744249, 2023). "Intriguingly, drug-tolerant persister cancer cells or mesenchymal cancer cells resistance to therapyare vulnerable to ferroptosis, which is likely to be associated with their dependence on GPX4 function." (PMID 37795022, 2023). "Cancer cells can also counter their susceptibility to ferroptosis by regulating GPX4 in the ferroptosis pathway." (PMID 37248295, 2023). "GSH depletion is essential for xCT inhibitor-induced ferroptosis, and GPx4 activity and intracellular iron levels are associated with sensitivity to ferroptosis in cancer cells." (PMID 37511540, 2023). "GPX4 is an essential regulator of ferroptosis, and the effects of ferroptosis on immunity, metabolism, inflammation, and cancer are associated with GPX4 and, the substrate of GPX4." (PMID 38130953, 2023). "It is worth noting that lower expression of FSP1 was observed in 559 cancer cell lines, and this decreased expression was associated with increased dependency on GPX4." (PMID 37371948, 2023). "A recent study reported that GPX4 was closely associated with ccRCC and conferred ferroptosis sensitivity to cancer cells." (PMID 38082448, 2023). "Collectively, these analyses suggested that GPX4 is associated with cancer immunotherapy in patients with COAD." (PMID 38065948, 2023). "Deletion of GPD2 in cancer cells increased their sensitivity to mitochondrial lipid peroxidation and ferroptosis caused by GPX4 inhibition." (PMID 38155662, 2023). "As a key peroxidation inhibiting protein, the activity of GPX4 is associated with a wide variety of diseases, including cancer and degenerative diseases." (PMID 35646948, 2022). "GPX4 is overexpressed in aggressive cancers, while its expression is inhibited by IDH1R132C mutation in cell lines." (PMID 35872783, 2022). "FSP1, formerly known as AIFM2, is a biomarker of ferroptosis resistance in many different cancers, protecting GPX4-deficient cells from ferroptosis." (PMID 35911967, 2022). "This study elucidated a regulatory mechanism that linked cystine/Cys availability to GPX4 protein synthesis and provided a new idea for using combinatorial therapy of ferroptosis inducers and mTORC1 inhibitors in cancer therapy." (PMID 35280684, 2022).
cancer (continued). "Featuring with high mesenchymal phenotypes, cancer cells of melanoma, prostate cancer and sarcomas, which are respectively resistant to the original cancer therapy, show upregulated susceptibility to GPX4-targeted ferroptosis." (PMID 35531466, 2022). "Elastin treatment of GPX4-knockout cancer cells is strongly associated with immune pathways such as the IL-1 and IL-2 pathways." (PMID 34975326, 2022). "One study showed that GPX4 activity plays an important role in several cancers driven by oncogenic mutations and dedifferentiated states." (PMID 36317423, 2022). "Inactivation of DHODH (knockout or inhibitor treatment) in cancer cells with low GPX4 expression causes severe mitochondrial lipid peroxidation and ferroptosis." (PMID 36429080, 2022). "The loss of GPX4 enhanced the toxic effects of mitochondrial inhibitors and sensitized cancer cells to ferroptosis." (PMID 35065965, 2022). "Various studies have reported that GPX4 is upregulated in different cancers, including LUAD, and is associated with poor prognosis of patients and chemotherapy resistance." (PMID 34926310, 2021). "Evidence proves that the loss of SIGMAR1 function can block the expression of GPX4 in vitro and in vivo to induce ferroptosis in cancer cells." (PMID 33867820, 2021). "Although numerous studies indicate loss of GPX4 induced ferroptotic cell death in cancer cells, deficiency of GPX4 also affects normal development or cell viability in normal tissue." (PMID 33731874, 2021). "By using an overexpression screen, their group demonstrated that FSP1 complemented the loss of GPX4 or inhibition of GPX4 in human cancer cells." (PMID 34945503, 2021). "While future studies should delineate the exact underlying mechanism, our finding that xCT positive cancer cells are simultaneously resistant to lipid peroxidation insult yet hypersensitive to xCT or GPX4 inhibitors raises important therapeutic implications." (PMID 33672555, 2021). "Glutathione peroxidase 4 (GPx4) has been implicated in the protection of cancer cells against ferroptosis and chemotherapeutic resistance." (PMID 34121995, 2021). "Glutathione peroxidase 4 (GPX4) is another selenoprotein with a 3′-UTR polymorphism implicated in cancer risk or mortality." (PMID 32806741, 2020). "For some proteins, e.g., SELENOF and GPX4, the encoded polymorphisms that are associated with cancer risk results in variations within the 3-UTR of the mRNA that controls UGA recoding and readthrough." (PMID 32806741, 2020). "Several recent studies have recently evidenced the role of QRs in cancer cells using a GPX4 deficiency model and have highlighted the potential of ubiquinol and, therefore, QRs as novel targets for cancer treatment." (PMID 33167334, 2020). "A study in 60 cancer cell lines from eight different tissues showed that ccRCC is particularly susceptible to GPX4-regulated ferroptosis, compared with the other tissues examined." (PMID 33362855, 2020). "Iron-dependent cell death (ferroptosis) was originally identified as a new form of regulated cell death in RAS-mutated cancer cells, and occurs when intracellular glutathione peroxidase 4 (GPX4) is inhibited directly or indirectly by a decrease in GSH levels." (PMID 32094346, 2020). "Although therapy-resistant mesenchymal-high cancers are particularly vulnerable to ferroptosis inducers, especially phospholipid glutathione peroxidase 4 (GPx4) inhibitors, the underlying mechanism is yet to be deciphered." (PMID 31527591, 2019). "GPx4 is the only selenoprotein which is consistently associated with a prolonged survival in cancer including HCC." (PMID 29515790, 2018). "The gene fusion of GPX4-MPND causes up-regulations of mRNA expression of both genes in primary cancer." (PMID 26330360, 2015). "The study’s findings suggest that GPX4 could emerge as a novel diagnostic biomarker for certain cancers, given its remarkable ability to distinguish between cancerous and healthy tissues." (PMID 41142608, 2025).
cancer (continued). "GPX4 activity is implicated in persistent drug tolerance or therapy resistance in various cancers." (PMID 40595451, 2025). "The loss of GPx4 in Treg cells impairs immune tolerance and promotes antitumor immunity, suggesting that targeting Gpx4 could be a strategy to increase cancer treatment by modulating Treg cell function." (PMID 39942544, 2025). "Loss of DHODH promotes ferroptosis, particularly in cancer cells with low GPX4 expression levels." (PMID 41326356, 2025). "Furthermore, we detected a correlation between the mutation burden of GPX4 across different types of cancer and patient survival outcomes." (PMID 41142608, 2025). "Regarding HR deficiency, recent work has shown that BRCA1-deficiency may be important to the response of cancer cells co-treated with a GPX4 and PARP combination, where GPX4 inhibition can induce ferroptosis." (PMID 40568132, 2025). "Previous studies have shown that the high expression of ALOX5 is closely associated with ferroptosis sensitivity, and ferroptosis is also closely linked to chemoresistance in cancer cells, with chemoresistant cancer cells being more susceptible to GPX4 inhibition." (PMID 41184226, 2025). "The aberrant regulation of key factors involved in ferroptosis and their regulators is closely linked to cancer progression, and targeting the ferroptosis network, particularly GPX4 and SLC7A11, may offer new therapeutic options for cancer and other diseases." (PMID 39771583, 2024). "Similarly, another research demonstrated that the cancer-causing component circDTL increases the expression of GPX4 by capturing miR-1287-5p, hence preventing ferroptosis and apoptosis." (PMID 39036600, 2024). "Consequently, GPX4, which exhibited abnormal expression in various cancers and held significant weight in the “risk score,” was chosen as the starting point for further investigation." (PMID 38312660, 2024). "And GPX4 expression was partly associated with the individual cancer stages of LUAD and LUSC." (PMID 38561419, 2024). "This FSP1 gene can complement the loss of GPX4 in cancer cells." (PMID 38313306, 2024). "Additionally, RSL3 inhibits GPX4, and the loss or inhibition of GPX4 induces ferroptosis in cancer cells." (PMID 37773303, 2024). "Combined, these results support that GPx4‐mediated cellular redox homeostasis in OC cells is linked to SR‐B1 expression levels and cholesterol accumulation, providing a rationale for targeting cholesterol uptake in Pt‐R cancer cells to induce ferroptosis." (PMID 38263873, 2024). "Loss of GPX4 may result in the death of iron in the refractory carcinoma cells due to various cancers and therapies." (PMID 38023171, 2023). "GPX4-regulated ferroptosis is involved in cancer development and progression, drug-resistant persistent cells are highly dependent on GPX4 for survival, and loss of GPX4 function leads to cellular ferroptosis and prevents drug resistance; thus, a novel avenue of cancer therapy is proposed." (PMID 37762411, 2023). "Additionally, cucurbitacin B, glycyrrhetinic acid, and ophiopogonin B can increase lipid peroxidation levels and cause ferroptosis in cancer cells through GPX4-GSH-related pathways." (PMID 37833746, 2023). "Since then, several reports have implicated GPX4 in cancer prognosis." (PMID 36576648, 2023). "In addition, arginine-capped manganese silicate nanobubbles (AMSNs) are nano-iron inducers that accelerate the depletion of GSH and cause the inactivation of GPX4, thereby inducing ferroptosis in cancer cells." (PMID 37739961, 2023). "Therefore, a reduction in targets of Nrf2 (an upstream transcriptional regulator of SLC7A11 and GPx4) makes cells susceptible to the activity of proferroptotic agents in some types of cancer." (PMID 38139106, 2023). "Furthermore, GSH depletion has been linked to reduced GPx4 activity and ferroptosis in cancer cells." (PMID 36768241, 2023). "This suggests that the ultimate identity of GPX4 could be an unconfirmed oncogene causing harm to patients with various cancers." (PMID 36675129, 2023).
cancer (continued). "Glutathione peroxidase 4 (GPX4) provides cell protection from oxidative stress-induced cell death and may be found in high levels in cancer cells, causing resistance to chemotherapeutics." (PMID 35721477, 2022). "Second, cancer cells may be more susceptible to GPX4 inhibition due to a higher level of polyunsaturated fatty acid (PUFAs) and enhanced susceptibility to lipid peroxidation, which requires a steady need for GPX4." (PMID 36358931, 2022). "The association between GPX4 and cancer OS has been investigated." (PMID 36443446, 2022). "Despite the crucial role of GPX4 in ferroptosis, certain cancer cells are resistant to ferroptosis caused by GPX4 inhibitors, suggesting that ferroptosis may also be regulated by other factors." (PMID 36506514, 2022). "Ferroptosis has significant importance during cancer treatment because of the combination of factors, including suppression of the glutathione peroxidase 4 (Gpx4), cysteine deficiency, and arachidonoyl (AA) peroxidation, which cause cells to undergo ferroptosis." (PMID 35408533, 2022). "In addition, the expression of GPX4 was reported associated with chemoresistance of anti-cancer drugs, including topotecan and lapatinib." (PMID 36276158, 2022). "Recent research has also demonstrated that cancer cells in a highly mesenchymal state are highly sensitive to the inhibition of GPX4, which means that CSCs might be more susceptible to ferroptosis-inducing agents than bulk cancer cells." (PMID 35053196, 2021). "In addition, drug-tolerant persister cells are highly dependent on GPx4 for survival, and loss of GPx4 function contributes to ferroptotic cell death and prevents drug resistance, suggesting a novel therapeutic avenue in cancers." (PMID 34611144, 2021). "After the upstream regulation of GPX4 was analyzed, high GPX4 levels in cancer cells may be associated with epigenetic regulation, such as DNA methylation and histone methylation or acetylation." (PMID 33574983, 2021). "Therefore, SLC7A11 likely represents a better therapeutic target for cancer treatment than GPX4 because inhibiting SLC7A11 would presumably cause less toxicity in patients than inhibiting GPX4." (PMID 34162423, 2021). "GPX4 is an essential seleno-protein shown to be associated with aging and cancer." (PMID 34767591, 2021). "Many types of cancer especially therapy-resistant cancer cells are sensitive to GPX4 deficiency." (PMID 34267193, 2021). "Although GPx4 plays a crucial role in ferroptosis, certain cancer cell lines are resistant to ferroptosis caused by GPx4 inhibitors, indicating that there might be additional factors that regulate ferroptosis." (PMID 32100402, 2020). "Thus, several AR-positive PCa cell lines demonstrated increased dependency on GPX4 activity in response to ATTs, a characteristic previously shown to be associated with drug-induced persister cells in other types of cancer in response to different therapies." (PMID 32577235, 2020). "Notably, cancer cells with VHL mutations exhibited greater dependence on GPX4 than VHL wildtype cells in a pan-cancer DepMap analysis." (PMID 30962421, 2019). "Although this pilot study had not the objective of associating the genetic variation in selenoprotein genes with risk of diseases, it should be noted that the polymorphisms mentioned here, mainly GPX1 rs1050450 and GPX4 rs713041, have been associated with cancer risk." (PMID 27164132, 2016). "The association of GPX4 with the human cancer is controversial." (PMID 26330360, 2015). "However, the high levels of xCT and GPX4 in cancer cells may cause cell proliferation and inhibit ferroptosis." (PMID 40732297, 2025). "Additionally, GPX4 expression was significantly correlated with the infiltration of cancer-associated fibroblasts (CAFs) in ESCA, HNSC, STAD, and TGCT, neutrophils in CESCs and HNSCs, B cells in HNSC-HPV+ and TGCT, CD8+ T cells in HNSC-HPV+, and regulatory T cells (Treg) in HNSC." (PMID 41142608, 2025).
cancer (continued). "Consequently, GPX4 could serve as a valuable tool in cancer risk prediction by offering a prognostic indicator for various types of cancer." (PMID 41142608, 2025). "Thus, measuring the GSH/GSSG ratio in cancer cells can reveal their state of oxidative stress and consequently predict their potential susceptibilities to ROS-inducing and antioxidant-depleting therapies such as GPX4 inhibitors and system XC inhibitors." (PMID 40943388, 2025). "In contrast, cancers with low GPX4 expression might be more susceptible to ferroptosis inducers." (PMID 38594779, 2024). "Thus, the compound could serve as an important candidate in cancer therapy by selectively elevating the level of Fe2+, causing lipid peroxidation and GPX4 degradation and finally inducing ferroptosis." (PMID 38698113, 2024). "Furthermore, it is necessary to consider that inhibiting CAT, GPx4, Prxs, TrxR, and other antioxidant enzymes can cause adverse reactions in other organs and tissues, which hinders their widespread application in human cancer." (PMID 38891864, 2024). "More convincingly, emerging evidence also supported that the loss of GPX4 strengthened the sensitivity of tumor cells to chemotherapy, hormone therapy, radiotherapy, and immunotherapy, which, together, reinforced the feasibility of targeting ferroptosis in different cancers." (PMID 39061847, 2024). "Additionally, GPX4, which is overexpressed in cancer tissues compared to normal tissues, is linked to decreased DNA methylation and an increase in H3K4me3 and H3K27ac marks at its promoter region, indicating that epigenetic regulation significantly contributes to the aberrant overexpression of GPX4." (PMID 39595619, 2024). "Therefore, exploring the role of GPX4 phosphorylation/dephosphorylation modification in ferroptosis might provide an attractive intervention strategy for ferroptosis-associated cancer treatment." (PMID 37554285, 2023). "GPX4 has been reported to be overexpressed in cancer tissues compared to normal tissues and to be associated with low levels of DNA methylation and enrichment of H3K4me3 and H3K27ac marks at its promoter, suggesting that epigenetic regulation may be involved in its aberrant overexpression." (PMID 37497000, 2023). "Therefore, by increasing ACSL4 expression and the rate of lipid peroxidation, RB1 loss raises the extent that cancer cells depend on GPX4 to block ferroptosis and, on the other hand, sensitizes cancer cells to GPX4 inhibitors or, in general, ferroptosis inducers." (PMID 37183818, 2023). "In addition, GPX4 has been linked to multiple cancers because of its cancerous effects." (PMID 36691638, 2023). "GPX4 increase could be beneficial to reduce cancer-associated oxidative stress." (PMID 35903697, 2022). "Importantly, SAA restriction in cancer may impair the glutathione (GSH)/GPX4 system, thus increasing the susceptibility to iron-mediated lipid peroxidation and in turn to ferroptosis." (PMID 36613691, 2022). "The side effects of statin treatment could be attributed to reduced levels of GPX4 in some tissues, while the decreased incidence of several cancers on statin consumption and the loss of GPX4 detected in some cancer cells with statin treatment could be ascribed to repression of GPX4 synthesis." (PMID 33868986, 2021). "More importantly, we delineate a "spatial topological" landscape of GPX4 to fully harness its therapeutic potential in cancer therapy." (PMID 42244975, 2026). "Degradation of peroxides, in particular by GPX4, the master regulator of ferroptosis, is currently receiving a lot of attention owing to its potential in cancer or degenerative disorders." (PMID 41719757, 2026). "In cancer research, targeting GPX4 has been used to induce ferroptosis for tackling cancer resilience." (PMID 41541703, 2026). "Future studies will explore the potential mechanisms for the protective effect of GPx4 in cancer cachexia." (PMID 41854231, 2026).